TNF (tumor necrosis factor)
Diseases named in the same sentence as TNF in open-access papers (continued):
Sharing a sentence is not in itself a finding about the gene and the disease.
cerebral edema (continued). "After traumatic brain injury (TBI), Cerebrolysin enhances neurological scores, lowers cerebral edema, improves BBB permeability, and reduces inflammatory cytokines such as TNF-α, IL-1β, IL-6, and NF-κB." (PMID 40362194, 2025). "The thorough investigation of fatal brain edema cases during CAR-T cell therapy could identify different associated risk factors, such as younger age, higher CD8 ratio, higher IL-15 serum concentrations, and low platelets before infusion, as well as rapid expansion and higher IL-2 and TNF-α peak." (PMID 36970518, 2023). "After TBI, inflammatory factors such as TNF-α, IL-1, and IL-6 are secreted and can induce oxidative stress responses and apoptosis, resulting in blood-brain barrier (BBB) impairment and cerebral oedema." (PMID 33381552, 2020). "CCHF infection can cause endothelial cell dysfunction (with increased vascular permeability) through the induction of cytokines (tumor necrosis factor-α, interleukin-6, interleukin-10, interferon [IFN]-γ), which can result in cerebral edema." (PMID 25529825, 2015). "In our study, ICT treatment decreased the expression of IL-1β and TNF-α while increasing the level of IL-10, indicating that ICT inhibited neuroinflammation and cerebral edema induced by tMCAO in rats by decreasing proinflammatory cytokine levels and increasing anti-inflammatory cytokine levels." (PMID 36447154, 2022). "Starting exercise soon after the TBI (within 24 h) may help protect against brain edema and improve learning and memory by reducing cell death in specific brain regions (CA1 and CA3) and also decreasing TNF‐α and MDA compared to starting exercise later (1 week after)." (PMID 40079502, 2025). "Additionally, TBI can induce the upregulation of Nuclear factor kappa-B (NF-κB), IL-1β, IL-6, tumor necrosis factor-α (TNF-α) and other target genes involved in ferroptosis, as well as the expression of AQP4, leading to increased disruption of the BBB and exacerbation of traumatic brain edema." (PMID 38250705, 2024). "We obtained preliminary conclusions from serum indicators of clinical patients that miR-7-5p may affect brain edema, but it does not affect MMP-9, ZO-1, occludin, IL-6, TNF-α, NLR, and CRP expression to affect the formation of brain edema." (PMID 33392188, 2020).
glomerulosclerosis (41 papers, 2013 to 2025). A hardening of the kidney glomerulus caused by scarring of the blood vessels. "These include renal tubulointerstitial fibrosis and glomerulosclerosis, as well as arteriosclerosis, amyloid deposition, and renal inflammaging caused by oxidative stress and proinflammatory cytokines, including interleukin-6 and tumor necrosis factor-α." (PMID 35646947, 2022). "Moreover, TNF-α can cause inflammation of renal tissue, collagen deposition, and glomerular sclerosis, leading to kidney injury." (PMID 34035828, 2021). "Cytokines and chemokines released during inflammation (e.g., IL-6 and TNF-α) directly damage glomerular and tubular cells and promote mesangial cell proliferation and matrix deposition, ultimately leading to glomerulosclerosis." (PMID 40130253, 2025). "In a study on glomerulosclerosis in aged female mice, it was found that elevated TNF-α in the serum and increased NF-κB in senescent glomerular mesangial cells led to a shift towards a pro-inflammatory phenotype." (PMID 39781471, 2025). "HDL-C can suppress the release of pro-inflammatory mediators like tumor necrosis factor-α and interleukin-6 while enhancing superoxide dismutase activity to alleviate oxidative stress, delaying glomerulosclerosis and tubulointerstitial fibrosis." (PMID 40483478, 2025). "Activated leukocytes secrete many kinds of cytokines and transcription factors that have a crucial role in inflammation—including TNF-, TNF-B, interleukin-1, and transforming growth factor—thereby contributing to glomerulosclerosis." (PMID 37370958, 2023). "In high fat diet-induced kidney injury, TNF-α deletion reduced kidney fibrosis, glomerulosclerosis, oxidative stress, inflammation and apoptosis." (PMID 34307414, 2021). "TWG alleviates glomerulosclerosis by exerting antimicroinflammatory effects, including reducing macrophage infiltration in the glomeruli, suppressing TNF-α, IL-1β and TGF-β1 overexpression in the kidney and inhibiting p38 MAPK and NF-κB signaling activities." (PMID 30021637, 2018). "The proximal tubule epithelial cells produce and release pro-inflammatory cytokines such as TNFα and IL6, this contributing to the extent of interstitial fibrosis, tubular atrophy, glomerulosclerosis, glomerular loss and CKD." (PMID 27031710, 2016). "Cola drinking treatment induced glomerulosclerosis (+21%, p < 0.05), higher histopathological score (+13%, p < 0.05), and largely higher tubular expression of both IL-6 (7-fold, p < 0.001) and TNF-α (4-fold, p < 0.001)." (PMID 27340342, 2016). "A study on glomerulosclerosis suggested that TNF-α may increase macrophage infiltration in aged mice by promoting pro-inflammatory mesangial cells." (PMID 39781471, 2025). "Another animal study showed that TNF-α could result in renal dysfunction as well as glomerulosclerosis through enhanced glomerular oxidative stress in obese mice." (PMID 37710270, 2023). "Elevated TNF-α could lead to glomerulosclerosis and decreased renal function in patients with CKD by enhancing glomerular oxidative stress." (PMID 35386695, 2022). "On the other hand, in the rat's model that was subjected to unilateral nephrectomy and a high-salt diet, it was unfolded that fluid retention was associated with an increase in the renal inflammation with macrophage infiltration and tumor necrosis factor-α overexpression, and glomerular sclerosis." (PMID 35284436, 2022). "Similarly, TNF-α gene deletion or silencing attenuated kidney injury induced by high fat diet in mice by reducing fibrosis and glomerulosclerosis." (PMID 34307414, 2021). "During glomerulosclerosis resident cells secrete pro-inflammatory factors such as tumor necrosis factor alpha (TNF-α), interleukin 1 beta (IL-1β), and transforming growth factor beta (TGF-β) which promote ECM synthesis and myofibroblast accumulation in the glomerulus." (PMID 32340145, 2020).
glomerulosclerosis (continued). "Additionally, TNF-α and IL-1 were positively correlated with proteinuria levels, mesangial hypercellularity, and glomerulosclerosis, providing perceptions into the potential function of TNF-α in the pathophysiology of proteinuria and pathological alterations in NS25." (PMID 40813446, 2025). "In addition, they participate in the evolution of immune-mediated renal inflammatory diseases, such as glomerulonephritides (GN), glomerulosclerosis, and glomerular hypercellularity, since MCs under certain conditions produce inflammatory mediators, such as tumor necrosis factor (TNF)-α." (PMID 35624699, 2022). "TNF-α, the inflammatory mediator, has been proved to promote the glomerular hypertrophy, expansion of the mesangial matrix and thickening of the glomerular and tubular basement membranes, ultimately resulting in proteinuria, glomerulosclerosis and tubulointerstitial fibrosis." (PMID 29569980, 2018). "This disruption promotes lipid accumulation and macrophage foam cell formation, leading to the sustained release of pro-inflammatory cytokines such as TNF-α, IL-1β, and MCP-1, which accelerate glomerulosclerosis and tubulointerstitial fibrosis." (PMID 41282283, 2025). "And dietary fiber can promote the production of SCFAs, which can reduce inflammation levels such as IL-6 and TNF-α, alleviate fibrosis-promoting factors such as collagen and TGF-β, and fight against glomerulosclerosis." (PMID 37362429, 2023). "Inflammatory cytokines such as IFN γ, IL-6, and TNF overactivated STAT1, STAT3, and NF-κB transcription factors to promote glomerulosclerosis and renal interstitial fibrosis." (PMID 34194519, 2021). "Because our previous studies have supported a role for TNF-α from macrophages in proteinuria and glomerulosclerosis, the current experiments suggest that TNF-α derived from recruited macrophages, rather than podocytes, contributed to podocyte injury." (PMID 34369383, 2021).
Headache (41 papers, 2013 to 2025). Cephalgia, or pain sensed in various parts of the head, not confined to the area of distribution of any nerve. "Pieces of evidence have shown that TNF injection can cause headache, and TNF antibody has been shown to reduce pain in humans." (PMID 38213956, 2024). "In a recent study, neuroinflammation was implicated in the pathogenesis of headache, as increased levels of proinflammatory cytokines, such as interleukin-1β and tumor necrosis factor-α are involved in the immune responses associated with headache." (PMID 36498721, 2022). "For example, headaches are associated with elevated Tumor Necrosis Factor-α (TNF-α), Interleukin-10 (IL-10), Interleukin-1β (IL-1β), Interleukin-6 (IL-6), and Interferon-α (IFN-α) levels." (PMID 35053845, 2022). "CRP, TNF-α and IL-6 have been positively associated with migraine headache, a usual symptom of PMS22." (PMID 31624297, 2019). "Given that TNF promotes mechanical sensitization of meningeal nociceptors and CGRP release in trigeminal ganglion, CSD-induced upregulation of TNF may contribute to mechanisms underlying migraine headache." (PMID 36613527, 2022). "A clinical trial demonstrated that 400 mg/day of CoQ10 for three months reduced headache severity, frequency, and duration, as well as inflammatory markers like tumor necrosis factor-α (TNF-α) and calcitonin gene-related peptide (CGRP)." (PMID 40005953, 2025). "The reviewed RCTs targeting TNF-α via indirect means (fish oil + curcumin) achieved notable decreases in headache frequency, underscoring TNF’s relevance." (PMID 41377228, 2025). "Pro-inflammatory cytokines, including interleukin 1, tumor necrosis factor alpha, and interleukin 6, are known to activate brain nerve endings, resulting in the pain experienced as headaches." (PMID 41249949, 2025). "Chemotherapy activates glial cells, such as microglia and astrocytes, which release pro-inflammatory cytokines, including IL-6, TNF-α, and IL-1β, sensitizing pain pathways and contributing to headache development." (PMID 41516139, 2025). "As far as axSpA is concerned, we showed that the patients who experienced headache used anti-TNF-alpha therapy more frequently." (PMID 38397972, 2024). "We found that repetitive stress and dural injection of PACAP38 induced headache behaviour through TNF-a and TRPV1 pathways." (PMID 38802819, 2024). "In the late eighties and early nineties, clinical studies demonstrated that intravenously administered TNF produced headaches in patients with tumors." (PMID 36835524, 2023). "Evidence supports the role of TNFα in headache pathogenesis, including increased TNFα serum level during a migraine attack and headache induction following TNFα infusion." (PMID 35911910, 2022). "Their potential contribution to headaches was supported by data that application of IL-1β or TNFα on rat dura resulted in activation and sensitization of meningeal nociceptors." (PMID 34615455, 2021). "Headache can be induced after TNF injection, whereas TNF antibody was shown to reduce pain in humans." (PMID 34112082, 2021). "Activation of resident mast cells in the meninges and release of proinflammatory cytokines such as IL-1β, IL-6, TNF-α and several chemokines have been proposed to play major roles in the progression of migraine headache." (PMID 34615455, 2021). "During headache-free periods (interictal period), increased pro-inflammatory levels of IL-1β, IL-6, TNF-α, and chemokines such as IL-8, macrophage inflammatory protein-1α (MIP-1α), and C–C chemokine ligand 5 (CCL5) were observed in patients." (PMID 34445635, 2021). "One study demonstrated that malarial pathogenesis was associated with excessive production of pro-inflammatory cytokines, such as the tumor necrosis factor which induces headaches." (PMID 31615478, 2019). "As a result, we recognized totally 7 possible causing genes (CALCA, TGFBR2, TNF, ESR1, EDNRA, KCNK18, and MTHFR) of headache in the top 10 genes." (PMID 24991551, 2014).
Headache (continued). "This combination treatment improves the overall success rate of treatment, reduces scores related to nasal symptoms, such as congestion and runny nose, alleviates symptoms like headache and olfactory disorders, and decreases inflammatory indicators like TNF-α and IL-6." (PMID 39612467, 2024). "Here, we have shown that PACAP38-MrgprB2 induces stress-induced headache via TNF-a and TRPV1." (PMID 38802819, 2024). "Headache was associated with significant increase in CXCL10, CXCL11, MCSF, MCP-2 and TNF-alpha, while fatigue was associated with significant increases in CXCL10, MCP-4 and TNF-α." (PMID 38235127, 2023). "Previous studies have described the role of cytokines such as TNFα in headache pathophysiology." (PMID 35911910, 2022). "Plasma TNF-α is negatively correlated with anxiety scores, and the serum MIP-1 or MIP-1:CD14 ratio was reported to be associated with the pain index and the severity of headache." (PMID 34445635, 2021). "TNF-α and IL-13 showed moderate positive correlation with headache." (PMID 25343623, 2014). "This cohort should include comprehensive biomarker collection, including serial measurements of inflammatory cytokines (IL-6, TNF-α, IL-1β), CGRP levels, markers of blood–brain barrier disruption, and genetic polymorphisms that may influence drug metabolism or headache susceptibility." (PMID 41516139, 2025). "Headache occurrence during the early stages of COVID-19 infection could be attributed to excess pro-inflammatory cytokine release, e.g., interleukin 1 (IL 1) and tumor necrosis factor-alpha (TNF-α), which promote trigeminal neural network sensitization, a key event in headache pathology." (PMID 35053817, 2022). "Regarding the use of biological drugs, our findings indicate that among the patients with axSpA encountering headaches, there was a higher usage of anti-TNF-alpha therapy compared to the patients without headaches." (PMID 38397972, 2024). "A clinical trial analyzed IL-1beta, IL-6, and TNF-alpha in 24 h urine samples of female migraineurs during menstrual and non-menstrual migraine attacks and headache-free periods and compared them with those of non-headache controls." (PMID 36835524, 2023). "Furthermore, the most prevalent adverse events with IL-17/23 inhibitors and TNF-α blockers in meta-analyses, including injection site reaction, infections, nasopharyngitis, and headache, were not reported in DCS subjects in our study." (PMID 40383754, 2025). "Zika virus-infected subjects who reported headaches showed higher plasma levels of TNF-α, IL-17A, IL-2, IL-9, IL-12p70, MIP-1α, G-CSF, GM-CSF, and VEGF, and significantly higher levels of IL-5 (p = 0.0015) compared to those without headache." (PMID 29774022, 2018).
Hypoglycemia (41 papers, 1988 to 2026). A decreased concentration of glucose in the blood. "Hypoglycaemia caused a significant increase in LPS- or P3C-stimulated TNF-α and IL-1β production and a decrease in stimulated IL-10 production, which normalised after 24 h and none of which was modified by antecedent hypoglycaemia." (PMID 38331900, 2024). "Similar results were observed in this study; our data revealed that endotoxins cause significant systemic inflammation (upregulation of TNF-α, IL-6, and leptin in plasma) and metabolic alterations (body weight loss and severe hypoglycemia) in obese mice." (PMID 35056093, 2021). "Hypoglycemia also induces the production of several inflammatory markers, including interleukin(lL)-6, C-reactive protein, TNFα, IL-8, and endothelin-1, which can cause endothelial injury." (PMID 30813549, 2019). "Hypoglycemia in an elderly patient with non-Hodgkin’s lymphoma was associated with normal insulin and insulin-like hormone levels but high TNF-α levels." (PMID 26284064, 2015). "In addition, elevated levels of inflammatory factors such as TNF-α and IL-6 have been observed in hypoglycemia, causing an acute inflammatory state in the organism." (PMID 34899278, 2021). "In a rat model of lipopolysaccharide (LPS)-induced AKI, both HIF-1α and aquaporin-1 (AQP1) were significantly upregulated within 12 h, concomitant with hypoglycemia, enhanced glycolysis, and a pro-inflammatory shift (elevated IL-6/TNF-α and reduced IL-10)." (PMID 41602837, 2026). "Left ventricular ejection fraction, measured with TNF-alpha, IL-1, and troponin I, indicated acute heart failure in these patients, especially in cases of repeated hypoglycemia and uncontrollable COVID-19 infection." (PMID 40599143, 2025). "By simulating the affinity of the active ingredient to the target through molecular docking, we further determined that Akt1and TNF are the main targets of KCLE for hypoglycemia due to its lower binding energy with multiple active ingredients." (PMID 40076380, 2025). "This was further supported by the presence of profound hyperlactatemia, hypoglycemia and depleted liver glycogen stores, proving enhanced glucose utilization through glycolysis after a lethal TNF dose." (PMID 41132685, 2025). "Multiple factors are involved in the development of hypoglycemia-induced brain injury, such as oxidative stress, heightened production of reactive oxygen species, elevated levels of inflammatory factors like TNF-α and IL-6, and the activation of MMP9." (PMID 39004753, 2024). "At this time, infection of host cells (such as macrophages) according to MAP infiltration increases the secretion of proinflammatory cytokines, such as IFN-γ, TNF-α, and IL-1, and induces hypoglycemia; by reducing the availability of glucose in the host cell." (PMID 36795721, 2023). "A plausible mechanism for the development of hypoglycemia following ricin administration is that the toxin induces a rapid and profound inflammatory response including the rapid induction of TNF-α." (PMID 36548717, 2022). "We showed that the hypoglycemia likely results from suppression of the transcription of hepatic glucose-6-phosphatase, mediated by TNF-α." (PMID 36548712, 2022). "The hypoglycemia is insulin- and TNF-α-independent and is paralleled by exhaustion of hepatic glycogen stores without increased gluconeogenesis." (PMID 30375380, 2018). "We demonstrated that the expression of TNF-α, IL-1β, and IL-6 was increased following acute severe hypoglycemia." (PMID 29793504, 2018). "It is well known that hypoglycemia-induced release of proinflammatory factors, including TNF-α, IL-1β, and IL-6, plays a critical role in BBB damage." (PMID 29793504, 2018). "Why these comorbidities are seen more often in patients with PsA, as opposed to other inflammatory arthritides, and why only certain patients treated with anti-TNF-α agents experience significant hypoglycemia remains a topic of further investigation." (PMID 29721512, 2017).